TBCEL (tubulin folding cofactor E like)
Description:
Acts as a regulator of tubulin stability.
Synonyms: EL; LRRC35; MGC10233
Tractability: PROTAC: ubiquitination databases record sites on it; its protein half-life has been measured.
Gene: Protein-coding gene on chromosome 11 (121,024,072 to 121,090,776, forward strand). Ensembl gene ENSG00000154114.
Subcellular location: Cytoplasm, cytoskeleton
Subcellular location (Human Protein Atlas): Cytosol
Gene Ontology:
Molecular function: protein binding; alpha-tubulin binding
Biological process: microtubule cytoskeleton organization; post-chaperonin tubulin folding pathway; tubulin complex assembly
Cellular component: cytoplasm; cytoskeleton
Genetic constraint (gnomAD): Loss-of-function variants: 14 observed, 42.69 expected, observed/expected ratio (o/e) 0.33, 90% interval 0.22 to 0.51. The upper end of that interval is the gene's LOEUF score, 0.51, which puts it in group 2 of 6, group 1 being the genes least tolerant of losing a copy. Missense variants: 314 observed, 518.88 expected, observed/expected ratio (o/e) 0.61, 90% interval 0.55 to 0.66. Synonymous variants: 167 observed, 192.18 expected, observed/expected ratio (o/e) 0.87, 90% interval 0.76 to 0.99.
Homologues: Orthologues: chimpanzee TBCEL (99% identical), dog TBCEL (99% identical), pig TBCEL (98% identical), guinea pig TBCEL (98% identical), mouse Tbcel (97% identical), rat Tbcel (97% identical), rabbit TBCEL (91% identical), tropical clawed frog tbcel (79% identical), zebrafish tbcelb (64% identical), Drosophila melanogaster mlt (40% identical), Caenorhabditis elegans coel-1 (29% identical), zebrafish tbcela (25% identical). Paralogues in human: TBCE (26% identical).
Diseases named in the same sentence as TBCEL in open-access papers:
TBCEL is named in the same sentence as 1 disease in open-access papers, as found by Europe PMC text mining. Sharing a sentence is not in itself a finding about the gene and the disease. The quoted sentences say what the papers report.
cyst (1 paper, 2020). A sac-like closed membranous structure that may be empty or contain fluid or amorphous material. "We employed the tub-Gal4 driver, which had been previously shown to drive expression through the spermatocyte stage and also in cyst cells through spermatid elongation, to express TBCEL in mulet mutant backgrounds and rescue individualization." (PMID 32033965, 2020).